NLRP3 (NLR family pyrin domain containing 3)
Diseases named in the same sentence as NLRP3 in open-access papers (continued):
Sharing a sentence is not in itself a finding about the gene and the disease.
E. coli infection (continued). "In conclusion, in this study, E. coli infection resulted in excessive activation of NLRP3 inflammasome and inhibited autophagy, while pretreatment with L. johnsonii L531 ameliorates E. coli–induced inflammation and cell damage in PMEC model." (PMID 32823867, 2020). "The same results were also found in the NLRP3-lentiviral vector-infected DEFs, especially after E. coli infection." (PMID 30349536, 2018). "In contrast to NLRP3 activation in response to diverse stimuli, upon E. coli infection, NLRC4 responds to bacterial rod protein of the T3SS apparatus and flagellin." (PMID 30087667, 2018). "We found that E. coli infection also increased the expression of NLRP3 protein from 1.5 to 6 h, but L. rhamnosus GR-1 pretreatment inhibited this increase." (PMID 30087667, 2018). "The results show that IL-1β, IL-18, and TNF-α in the liver, spleen, and brain of the NLRP3-lentiviral vector-injected group mostly increased after E. coli infection." (PMID 30349536, 2018). "Our findings indicate that E. coli infection activates caspase-4, subsequently resulting in cell pyroptosis and maturation of IL-1β and IL-18 via an NLRP3 inflammasome-dependent and ASC-independent pathway." (PMID 30087667, 2018). "Our study demonstrated that Ybt-induced E. coli infection led to intestinal epithelial cell pyroptosis via the NLRP3 pathway, resulting in the release of large amounts of IL-1β and IL-18, which promoted gut inflammation and contributed to E. coli-induced intestinal damage." (PMID 37511208, 2023). "Given the role of NLRP3 in E. coli infection, we screened drugs targeting NLRP3 using a drug library and identified candidates that effectively bind to NLRP3 (e.g., digitoxin, a cardiotonic drug), providing a list of potential drugs for treating E. coli-induced gut inflammation in the future." (PMID 37511208, 2023). "Furthermore, it was demonstrated that E. coli infection mediated the inflammatory response through activation of NLRP3 and NLRC4 inflammasome in bovine mammary epithelial cells." (PMID 35893774, 2022). "L. johnsonii L531 inhibits the activation of NLRP3 inflammasome during E. coli infection." (PMID 32823867, 2020). "We hypothesized that during E. coli infection, the activity of NLRP3 and NLRC4 inflammasomes is differentially regulated by L. rhamnosus GR-1, inducing maturation of IL-1β and IL-18 or cell pyroptosis, depending on ASC." (PMID 30087667, 2018). "In the present study, a PMEC model of E. coli infection was established to test the hypothesis that L. johnsonii L531 attenuates E. coli–induced inflammation and cell damages by restricting NLRP3 inflammasome activity and promoting ATG5/ATG16L1–mediated autophagy in PMECs." (PMID 32823867, 2020). "Our results showed that NLRP3, caspase-1, GSDMD, and IL-1β were significantly upregulated in response to E. coli infection, with KEGG enrichment revealing that upregulated genes were mainly concentrated in the NOD-like receptor signaling pathway." (PMID 37511208, 2023). "Accompanying the decrease in ROS, NLRP3, Caspase-1 p10, and Caspase-3 p17 levels due to E. coli infection was mitigated by NAC, which indicated that E. coli-induced NLRP3 inflammasome and apoptosis activation required ROS production." (PMID 34594329, 2021). "Among avian species, cherry valley duck NLRP3 was cloned and functionally characterized, where overexpression of duck NLRP3 in DEF cells had an anti-bacterial effect towards Escherichia coli infection and enhanced the upregulation of IL-1β, IL-18, and TNF-α." (PMID 32012730, 2020). "We provide evidence that L. rhamnosus GR-1 suppresses E. coli-induced ASC-dependent activation of NLRP3 and NLRC4 inflammasomes and thus decreases production of IL-lβ and IL-18 during E. coli infection." (PMID 30087667, 2018). "Caspase-11 is activated via NLRP3-independent mechanisms, but it is essential for NLRP3-dependent and ASC-dependent caspase-1 processing and IL-1β maturation in response to E. coli infection." (PMID 30087667, 2018).
E. coli infection (continued). "Western blot analysis demonstrated increased expression of NLRP3 and NLRC4 following E. coli infection, but this increase was attenuated by pre-incubation with L. rhamnosus GR-1, regardless of ASC knockout." (PMID 30087667, 2018). "L. rhamnosus GR-1 inhibits activation of ASC-dependent NLRP3 and NLRC4 inflammasome activation and production of the downstream proinflammatory cytokines IL-lβ and IL-18 during E. coli infection." (PMID 30087667, 2018). "Our data indicate that L. rhamnosus GR-1 suppresses activation of ASC-dependent NLRP3 and NLRC4 inflammasomes and production of downstream IL-lβ and IL-18 during E. coli infection." (PMID 30087667, 2018). "In response to E. coli infection, neither Nlrp3 nor Il1b mRNA levels were decreased in Casp6−/− BMDMs compared with those in WT BMDMs." (PMID 34740613, 2021). "Lactobacillus rhamnosus GR-1 suppresses ASC-dependent NLRP3 inflammasome activation and ASC-independent caspase-1 processing by inhibiting caspase-4 activation, thereby attenuating cell pyroptosis and cytokine production and thus preventing establishment of E. coli infection." (PMID 30087667, 2018).
Huntington disease (20 papers, 2018 to 2026). Huntington disease (HD) is a rare neurodegenerative disorder of the central nervous system characterized by unwanted choreatic movements, behavioral and psychiatric disturbances and dementia. "R6/2 mice (transgenic mice of Huntington’s disease) with Gal3 gene mutation in the striatum reduced the number of mHTT and inhibited NLRP3 inflammasome activation in the microglia, mitigating the effects of neuronal damage." (PMID 36009120, 2022). "Gal3 damaged neurons by improving the secretion of NLRP3 inflammasome and IL-1β in the mice model of Huntington’s disease." (PMID 36009120, 2022). "NLRP3 inflammasome inhibition or the use of other immunosuppressive agents reduces the pathophysiological changes in Huntington’s disease." (PMID 36009120, 2022). "Galectin-3 controls the severity of inflammation and induces the activation of NLRP3 inflammasome-dependent pathways in Huntington's disease and spinal cord injuries." (PMID 34720894, 2021). "On this matter, long-term treatment with MCC950, a highly selective inhibitor of NLRP3, was shown to be beneficial in the treatment of mood disorders, neurodevelopmental diseases, and neurodegenerative diseases such as Alzheimer’s and Huntington’s disease." (PMID 38892585, 2024). "However, further efforts are demanded in the investigation of the NLRP3 inflammasome in the treatment of Huntington’s disease." (PMID 30233319, 2018). "In adult Huntington’s disease mice, the up-regulation of GAL-3 formed puncta in damaged lysosomes in primary microglia and contributed to inflammation through NF-κB and NLRP3 inflammasome-dependent pathways." (PMID 36980197, 2023). "NLRP3 inflammasome inhibition by MCC950 decreases microglial inflammatory vesicle activation in mice, protects DA neurons in the substantia nigra, and suppresses motor dysfunctions in the mice model of Huntington’s disease." (PMID 36009120, 2022). "Unlike in healthy individuals, NLRP3 inflammasome levels significantly increase in peripheral blood mononuclear cells (PBMCs) in patients with Huntington’s disease." (PMID 36009120, 2022).
mood disorder (20 papers, 2016 to 2026). A cognitive disorder a disturbance in which the person's mood is hypothesized to be the main underlying feature. "The activation of the NLRP3 inflammasome may be responsible for maintaining a persistent neuroinflammatory state in the CNS, which may be associated with behavioral or mood disorders and neurodegeneration diseases." (PMID 38892585, 2024). "Thus, it has been suggested that NLRP3 plays a key role in mood disorders associated with neuroinflammation." (PMID 33303808, 2020). "We have also previously reported increased protein expression of NLRP3 in post-mortem brain tissue of BD patients and that PBMCs of patients with mood disorders can be increasingly sensitive to NLRP3 activation, possibly due to underlying inflammation." (PMID 40854880, 2025). "To date, we identified seven articles investigated NLRP3 inflammasome activation in neuropsychiatric patients suffering from mood disorders, including major depressive disorder (MDD) and bipolar disorder." (PMID 34830395, 2021). "Across studies investigating these mood disorders, the techniques used to measure the NLRP3 inflammasome were real-time quantitative reverse transcription polymerase chain reaction (qRT-PCR), enzyme linked immunosorbent (ELISA), and Western blotting." (PMID 34830395, 2021). "As evidenced by our literature overview, there is evidence to support upregulation of the NLRP3 inflammasome in mood disorders." (PMID 34830395, 2021). "Altogether, these findings suggest that inflammatory cytokines and NLRP3 inflammasome may act as key neuromodulators in neurochemical and physiological alterations that underlie development and maintenance of behavioral deficits associated with both mood disorders and systemic illnesses." (PMID 26977323, 2016). "Mechanistically, the TLR-4/NF-κB and NLRP3 inflammasome signaling pathways partially mediate this interaction, highlighting the intricate relationship between gut microbiota, inflammation, and mood disorders." (PMID 39741947, 2024). "In this context, this narrative review presents an overview of preclinical and clinical studies that support a role of the NLRP3 inflammasome in the pathogenesis of MDD, highlighting that pathways related to NLRP3 inflammasome represent promising strategies for the treatment of this mood disorder." (PMID 36613574, 2022). "The inter-individual differences in activation magnitude may inform individualized therapeutic treatments to control the level of NLRP3 activation in patients with mood disorders and other related diseases." (PMID 34830395, 2021). "Taken together, these findings highlight NLRP3 inflammasome inhibition as a convergent and critical pathway through which AdipoRon exerts its neuroprotective and antidepressant effects, reinforcing the inflammasome’s role as a promising therapeutic target with AdipoRon in mood disorders." (PMID 40868122, 2025). "We have outlined a process for assessing NLRP3 inflammasome activation, applied the technique in PBMC from adolescents with mood disorders, and validated the assay with measurements in cell culture media of corresponding samples." (PMID 34830395, 2021). "Overall, the studies report an increase in mRNA expression of NLRP3, ASC, and caspase-1 genes in mood disorder patient groups when compared to healthy controls." (PMID 34830395, 2021). "In early-stage mood disorder patients, we see that all PBMC are sensitive to NLRP3 activation, as evidenced by the significant increase in intracellular ASC specks and extracellular IL-1 beta production." (PMID 34830395, 2021). "There are no active clinical trials for patients with mood disorders using NLRP3 inhibitors, nor any psychiatric-purpose patents for NLRP3 inhibitors." (PMID 34830395, 2021).
mood disorder (continued). "Imbalance in the NLRP3 (NOD-like receptor family, pyrin domain containing 3) inflammasome in critical brain areas involved in pain perception, like the prefrontal cortex and hippocampus, may contribute to the development of mood disorders following spinal cord injury." (PMID 39518713, 2024).
acute coronary syndrome (19 papers, 2018 to 2026). Signs and symptoms related to acute ischemia of the myocardium secondary to coronary artery disease. "The NLRP3 expression was associated with adverse cardiac events including congestive HF in patients with acute coronary syndromes." (PMID 33804661, 2021). "Colchicine therapy in acute coronary syndrome patients acts on caspase‐1 to suppress NLRP3 inflammasome monocyte activation." (PMID 39912853, 2025). "Next, we analyzed the expression pattern of TFG and pyroptosis-associated genes caspase-1 and NLRP3 using GEO datasets (GSE10220), including 48 macrophage and 48 monocyte samples from 86 patients with symptoms of the acute coronary syndrome." (PMID 35091545, 2022). "Acute coronary syndrome patients with CCs in culprit lesions had a higher expression of NLRP3, IL-1β, and IL-18, and had more vulnerable plaque characteristics than patients without CCs." (PMID 36386333, 2022). "Elevated plasma IL‐37, IL‐18, and IL‐18BP levels are also observed in patients with inflammatory conditions, such as acute coronary syndrome, where NLRP3 is involved." (PMID 35429346, 2022). "As far as inflammasome activation occurs in two phases, it is presumed that in acute coronary syndromes ischemic injury is responsible for priming the NLRP3 and pro-IL-1β by locally released DAMPs." (PMID 35055149, 2022). "Myocardial necrosis in acute coronary syndromes releases cellular debris, which may act as DAMPs to activate NLRP3." (PMID 35055149, 2022). "Of note, colchicine, a NLRP3 inflammasome inhibitor, has been identified that exerts anti‐inflammatory properties in patients with acute coronary syndrome partly by blocking the activity of monocyte caspase‐1 and thereby inhibiting NLRP3 inflammasome activation." (PMID 33783966, 2021). "Colchicine, a potent non-specific anti-inflammatory drug, also lowers NLRP3 expression and serum levels of IL-1β and IL18 in patients with acute coronary syndromes." (PMID 35055149, 2022).
allergic rhinitis (19 papers, 2016 to 2026). Inflammation of the nasal mucous membranes caused by an IgE-mediated response to external allergens. "PM2.5 has also been linked to the exacerbation of nasal mucosal damage in allergic rhinitis mice through NLRP3-mediated pyroptosis." (PMID 38698414, 2024). "Molecular docking studies indicate that seven representative compounds of XQLD exhibit favorable binding properties to NLRP3, potentially inhibiting NLRP3 inflammasome-mediated pyroptosis in nasal mucosa and improving allergic rhinitis symptoms." (PMID 39131161, 2024). "The current evidence suggests that the NLRP3 inflammasome and its related cytokines promote the development of allergic rhinitis." (PMID 30940096, 2019). "These outcomes support the findings in rats with allergic rhinitis, further proving that APS inhibits the activation of NLRP3 inflammatory vesicles in rats, hence lowering the production of inflammatory markers (Caspase-1, IL-1β, and ASC)." (PMID 40427385, 2025). "miR-133b mimic was shown to attenuate allergic rhinitis by decreasing the levels of Th2 cytokines and NLR family pyrin domain containing 3 (Nlrp3)." (PMID 36430378, 2022). "In allergic rhinitis models, Rh1’s therapeutic efficacy operates through activation of the AMPK/ULK1/FUNDC1 pathway, which mediates mitochondrial autophagy and subsequently reduces NLRP3 inflammasome activation while restoring Th1/Th2 balance." (PMID 41155644, 2025). "In human nasal epithelial cell stress-based and mouse allergic rhinitis models, Polydatin ameliorated mitochondrial damage through PINK1-Parkin-mediated mitochondrial autophagy and exerted a protective effect against allergic rhinitis by inhibiting NLRP3 inflammatory vesicles." (PMID 38054830, 2023).
Candida infection (19 papers, 2011 to 2026). "NLRP3 activation is critical for antifungal defense; mice deficient in NLRP3 exhibit increased susceptibility to systemic candidiasis." (PMID 41404367, 2025). "NLRP3 inflammasome components were also studied in a model of mucosal Candida infection, with NLRP3-, ASC-, or caspase-1-deficient mice being more susceptible to invasive disease, given that they presented a higher fungal burden in the kidneys and the digestive system." (PMID 26204108, 2015). "For example, mtROS and oxidized mtDNA released during Candida infection serve as potent activators of the NLRP3 inflammasome, driving IL-1β and IL-18 secretion." (PMID 41404367, 2025). "Emerging evidence indicates that the NLRP3 inflammasome plays an indispensable role in the defense response to Candida infection." (PMID 37723958, 2024). "Mice deficient in NLRP3, ASC, or caspase-1 have increased fungal proliferation and decreased survival during systemic candidiasis." (PMID 34964702, 2022). "During systemic candidiasis, candidalysin contributes to NLRP3 inflammasome activation with subsequent caspase-1-dependent IL-1β secretion and renal neutrophil recruitment." (PMID 34964702, 2022). "Upon Candida infection, NLRP3-mediated inflammasome assembly is induced by key pattern recognition receptors and their downstream molecules, including TLR2, Dectin-1, Syk and ZBP142–44,105." (PMID 34795266, 2021). "Borghi and colleagues demonstrated that an IL-22/NLRC4/IL-1 receptor antagonist (IL-1Ra) axis controls NLRP3 activation during Candida infection." (PMID 33119702, 2020). "The components of the NLRP3 inflammasome as well as IL-1β, IL-18, and the IL-1α/IL-1β receptor IL-1RI, are important for host survival from systemic candidiasis and prevention of dissemination of oropharyngeal candidiasis." (PMID 24967821, 2014). "We show that Candida infection up-regulates NLRP3 and NLRC4 expression in mucosal tissues compared to mock infected mice." (PMID 22174673, 2011). "We and others have previously shown that the NLRP3 inflammasome is important for control of Candida infection in both mucosal and disseminated models." (PMID 22174673, 2011). "The cytokine IL-6 was induced in wild-type mice in response to Candida infection but was significantly reduced in NLRC4 deficient mice and completely abrogated in NLRP3 and ASC deficient mice." (PMID 22174673, 2011). "Taken together, our studies imply that NLRC4 and NLRP3 are differentially functioning in the innate response to Candida infection, with NLRC4 playing a more prominent role in the clearance of oral infection." (PMID 22174673, 2011). "However, reduced NLRP3 activity has been shown to impair antifungal immunity against Candida infection." (PMID 41596738, 2026). "However, in other settings, such as candidiasis, IL-9 has been shown to play a proinflammatory role by promoting NLRP3 inflammasome activity in the early stages of infection and, in the late stages, a tolerogenic role by promoting IL-1Rα production." (PMID 40962954, 2025). "Of note, NLRP3-independent non-canonical inflammasome activation has also been implicated in Candida infection." (PMID 34795266, 2021). "Mice that lack NLRP3 (Nalp3, Cryopyrin, CIAS1, and PYPAF1) were more susceptible to Candida infections, since the NLRP3 inflammasome aids in epithelial integrity, contributing to irritable bowel disease (IBD) in C. albicans yeast and hyphae morphologies, and leading to excess inflammation." (PMID 29518906, 2018). "Furthermore, targeted deletion studies suggest a key importance of syk in CD11c+ cells during systemic candidiasis implying that NLRP3 activation in CD11c+ cells governs candidiasis." (PMID 27994587, 2016). "We show that inflammasome driven IL-1β responses via both the NLRC4 and NLRP3 inflammasome are essential for epithelial antimicrobial peptide production, and other inflammatory responses including IL-18 and IL-17 in response to Candida infection." (PMID 22174673, 2011).